PLK4 (polo like kinase 4)
Diseases named in the same sentence as PLK4 in open-access papers (continued):
Sharing a sentence is not in itself a finding about the gene and the disease.
breast carcinoma (continued). "In conclusion, further investigations of the role of PLK4 in breast cancer pathogenesis and its response to treatment are warranted to better understand breast cancer biology and to develop better treatment strategies and novel therapeutic approaches in breast cancer." (PMID 41092110, 2025). "PLK4 shows great promise as a prognostic and predictive biomarker in breast cancer." (PMID 41092110, 2025). "Further pre-clinical and clinical development of these compounds might provide additional novel drugs against PLK4 to be tested in breast cancer." (PMID 41092110, 2025). "Interestingly, overexpression of Plk4 has also been shown to have a prognostic value associated with worse DFS and OS of breast cancer patients." (PMID 36797240, 2023). "In addition, Plk4 has been shown to promote cancer metastasis through the regulation of the actin cytoskeleton by the Arp2/3 complex in breast cancer cells, whereas its downregulation suppresses tumorigenesis and metastasis in neuroblastoma." (PMID 36797240, 2023). "Previous studies indicated that PLK4 was high expressed in several human cancers, including hepatocellular carcinoma, colorectal cancer, gastric cancer, glioblastoma, neuroblastoma, breast cancer, and lung cancer, and had a close relationship with the progression of cancers." (PMID 36051696, 2022). "PLK4 is overexpressed in colon and breast cancers and downregulated in hepatocellular carcinoma." (PMID 35256538, 2022). "Furthermore, combining RNA interference screening with gene expression analysis in human breast cancer cell lines identifies that the activity of PLK4 is crucial for human breast cancer proliferation." (PMID 30337519, 2018). "In addition to being a treatment target, PLK4 may also be valuable as a biomarker of response to cancer treatment including in breast cancer and rectal cancer." (PMID 41092110, 2025). "Targeting this motif in PLK4 with small molecules has been considered a therapeutic strategy for blocking centriole duplication in cancers that rely on PLK4‐driven centrosome amplification, which is frequently observed in certain cancers, particularly breast cancer and melanoma." (PMID 40257113, 2025). "Furthermore, YLT-11 could strongly regulate downstream factors of PLK4, which was involved in cell cycle regulation, ultimately inducing apoptosis of breast cancer cell." (PMID 30337519, 2018). "Major radiosensitizers relevant for breast cancer also include mTOR inhibitors, ATM inhibitors and PLK-4 inhibitors." (PMID 40667051, 2025). "Therefore, PLK4 may be a promising therapeutic target for the human breast cancer therapeutics." (PMID 30337519, 2018). "Here, we present a novel PLK4 inhibitor, YLT-11, and further investigate the functional characterization and the possible mechanism against human breast cancer." (PMID 30337519, 2018). "FOXM1 regulates XRCC1 and BRCA2 in HER positive breast cancer, in triple-negative breast cancer, however, FOXM1 transactivates EXO1 and PLK4 in response to doxorubicin." (PMID 24824601, 2014). "PLK4 expression is also reported to be a negative predictor of response to taxane-based neoadjuvant chemotherapy in breast cancer." (PMID 41092110, 2025).
breast carcinoma (continued). "For example, PLK4-driven centrosome amplified breast tumor cells have been reported to be highly sensitive to inhibitors of the STAT3 (signal transducer and activator of transcription 3) protein, an emerging potential therapeutic target in breast cancer." (PMID 41092110, 2025). "The role and mechanisms of PLK4 in regulating the tumor immune microenvironment, a known player in cancer development and progression, in breast cancer are not well-understood." (PMID 41092110, 2025). "A synthetic lethal relationship between PLK4 inhibition and TRIM37 overexpression in cancers with amplifications or gains of the chromosomal region 17q23, commonly observed in breast cancer and neuroblastoma, has brought PLK4 inhibitors into the spotlight as potential therapeutics." (PMID 40257113, 2025). "In the most aggressive breast cancer subtype, triple-negative breast cancer (TNBC), PLK4 has been reported to promote migration and invasion of cancer cells via its modulation by FEN1 (Flap endonuclease-1 (FEN1), a nuclease important for DNA replication and repair processes." (PMID 41092110, 2025). "The Chr17q region containing the centrosomal ubiquitin ligase TRIM37 gene has recently been shown to be frequently amplified in neuroblastoma and breast cancer, rendering these cancer types highly sensitive to Serine/Threonine Protein kinase PLK4 (Polo-like Kinase 4) inhibition." (PMID 33922633, 2021). "Interestingly, clinical data show that PLK4 and AURKB expression are increased in high-grade bladder cancer and correlate with reduced survival in breast cancer patients." (PMID 31142743, 2019). "Finally, we identified that PLK4 sensitives HCC to CFI‐400945, a small‐molecule inhibitor of PLK4 undergoing phase II clinical trial testing in breast cancer and prostate cancer, which provided a potential therapy target for HCC." (PMID 31489978, 2019). "Several studies report that PLK4 expression positively correlates with various worse clinical outcomes and clinicopathological parameters, such as higher incidence of lymph node and distant metastases and poorer OS, progression-free survival (PFS) and RFS in breast cancer patients." (PMID 41092110, 2025). "PLK4 was prevailing high expressed in the breast cancer, with only 2.6% samples being negative." (PMID 36051696, 2022). "Furthermore, quantitative reverse transcription polymerase chain reaction was used to compare PLK4 messenger RNA levels in breast cancer cell lines to the normal mammary cell, and the results demonstrated that PLK4 levels are significantly higher in breast cancer cells." (PMID 30337519, 2018). "Although the role of CAND1 in mediating invasion in breast cancer has not been investigated yet, CAND1 has been shown to stabilize and synergize with PLK4 to induce centriole overduplication in prostate cancer." (PMID 36292029, 2022).
neuroblastoma (28 papers, 2018 to 2026). Neuroblastoma (NB) is the most common solid, extracranial childhood tumor. "We show here that chromosome 17q/TRIM37 gain is a defining feature of high-risk neuroblastoma and renders patient-derived cell lines hypersensitive to the novel PLK4 inhibitor RP-1664." (PMID 42288516, 2026). "We show here that chromosome 17q/TRIM37 gain is a pathognomonic feature of high-risk neuroblastoma and renders patient-derived cell lines hypersensitive to the novel PLK4 inhibitor RP-1664." (PMID 40766251, 2025). "PLK4 harbored putative complementary sequences for miR-338-3p, and was selected for further exploration due to its association with the tumorigenesis of neuroblastoma cells." (PMID 32536824, 2020). "Previous study indicated PLK4 was up-regulated in neuroblastoma and deregulated PLK4 was associated with the tumorigenesis in neuroblastoma cells." (PMID 32536824, 2020). "The expression of PLK4 in neuroblastoma (NB) is associated with a poor prognosis and has been reported in both primary and metastatic forms, suggesting that PLK4 may accelerate tumorigenesis in NB." (PMID 36620611, 2022). "Pharmacological inhibition of PLK4 further confirmed its functional relevance in promoting neuroblastoma differentiation." (PMID 40860200, 2025). "RP-1664, a novel PLK4 inhibitor, shows antitumor activity in neuroblastoma xenograft models and prolongs survival in a transgenic murine neuroblastoma model." (PMID 41092110, 2025). "PLK4 has been reported to modulate sensitivity to various chemotherapeutic agents such as temozolomide in glioblastoma; cisplatin in neuroblastoma and oxaliplatin in colorectal cancer." (PMID 41092110, 2025). "Remarkably, PLK4 expression varied significantly across tumor types, with the highest levels observed in neuroblastoma, followed by ganglioneuroblastoma and ganglioneuroma." (PMID 40860200, 2025). "Through comprehensive analyses employing Western blotting, co-immunoprecipitation, immunofluorescence and murine neuroblastoma models, we identified downstream signaling pathways involved in PLK4-mediated regulation of neuronal genes." (PMID 40860200, 2025). "In neuroblastoma, Plk4 promotes EMT through PI3K/Akt signaling pathway, by downregulating E-cadherin and upregulating EMT-related factors, such as Snail/Slug." (PMID 36797240, 2023). "In neuroblastoma cells, PLK4 has been found to mediate epithelial–mesenchymal transition tumorigenesis and cisplatin resistance via PI3K/Akt signaling pathway." (PMID 35387563, 2022). "A study reported that lncRNA SNHG1 promoted tumorigenesis by increasing the level of PLK4 and sponging miR‐338‐3p in neuroblastoma." (PMID 35592755, 2022). "SNHG1 induced neuroblastoma cell proliferation and migration by miR-338-3p sponging resulting in PLK4 upregulation." (PMID 33827418, 2021). "Another line of evidence is from a very recent report that PLK4 up-regulation promoted epithelial cell state transition in neuroblastoma." (PMID 33778212, 2021). "Immediately, we further explored the potential molecular mechanisms by which SNHG16/miR-338-3p axis affecting cell cisplatin-resistant and carcinogenesis in neuroblastoma, and we found that PLK4 was a target of miR-338-3p." (PMID 32536824, 2020). "In this study, we validated SNHG16 positively modulated PLK4 expression by sponging miR-338-3p in cisplatin-resistant neuroblastoma cells." (PMID 32536824, 2020). "Subsequently, the level of PLK4 was detected and PLK4 was significantly increased in cisplatin-resistant neuroblastoma tissues and cells." (PMID 32536824, 2020). "SNHG16 contributed to the tumorigenesis and cisplatin resistance in neuroblastoma possibly through miR-338-3p/PLK4 pathway, indicating a novel insight for overcoming chemoresistance in neuroblastoma patients." (PMID 32536824, 2020).
neuroblastoma (continued). "In conclusion, our studies demonstrated that SNHG16 contributed to cell cisplatin resistance and tumorigenesis in neuroblastoma via regulating miR-338-3p/PLK4 axis, suggesting a therapeutic target against cisplatin resistance in neuroblastoma." (PMID 32536824, 2020). "In neuroblastoma, where PLK4 is found to be upregulated, its expression is negatively correlated with poor clinical and survival parameters, while PLK4 downregulation suppresses neuroblastoma cells migration and invasion by inhibiting EMT via the PI3 K/Akt signaling." (PMID 41092110, 2025). "Interestingly, high Plk4 expression has been shown to induce EMT in neuroblastoma and colorectal cancer by regulating PI3K/Akt and Wnt/ß-catenin signaling pathways, respectively, which are well-known oncogenic pathways." (PMID 36797240, 2023). "Here, this work aimed to explore the function of SNHG16 and miR-338-3p in neuroblastoma cell drug resistance, investigated the relationship between SNHG16 and miR-338-3p, as well as identify the means by which it mediating PLK4 to affect neuroblastoma drug resistance." (PMID 32536824, 2020). "In the present study, we also discovered SNHG16/miR-338-3p/PLK4 axis could regulate the activation of PI3K/AKT pathway in neuroblastoma cells." (PMID 32536824, 2020). "According to the regulatory network of miR-338-3p/PLK4, we wanted to investigate whether miR-338-3p/PLK4 axis was responsible for cell cisplatin resistance and tumorigenesis in neuroblastoma." (PMID 32536824, 2020). "Altogether, we confirmed that miR-338-3p could enhance the sensitivity of cisplatin-resistant neuroblastoma cells to cisplatin and suppressed cell tumorigenesis by regulating PLK4." (PMID 32536824, 2020). "Furthermore, PLK4 overexpression reversed the inhibitory effects of miR-338-3p on cisplatin resistance and malignant phenotype in neuroblastoma." (PMID 32536824, 2020). "Recently, we reported PLK4 overexpression in pediatric embryonal tumors including peripheral malignant rhabdoid tumors (RT), atypical teratoid rhabdoid tumors (AT/RT) of the brain, medulloblastomas (MB), and neuroblastoma of the CNS (CNS-NB)." (PMID 31035676, 2019). "Moreover, circKIF2A could sponge miR‐129‐5p to regulate the expression of PLK4 and promote neuroblastoma progression." (PMID 35592755, 2022). "Besides that, SNHG16 could regulate PLK4 expression by sponging miR-338-3p and SNHG16/miR-338-3p/PLK4 axis could affect the activation of PI3K/AKT pathway in cisplatin-resistant neuroblastoma cells." (PMID 32536824, 2020). "Therefore, a SNHG16/miR-338-3p/PLK4 regulatory network was identified in neuroblastoma." (PMID 32536824, 2020). "Thus, deeper investigations on PLK4 and miR-338-3p in neuroblastoma drug resistance are required." (PMID 32536824, 2020). "The upregulation of PLK4, a key regulator of centriole duplication, activates the PAM signaling pathway, resulting in the stimulation of neuroblastoma cell proliferation, migration, and autophagy." (PMID 38891878, 2024). "The effects of increased PLK4 expression are again mediated through the PAM signaling pathway, contributing to a resistant neuroblastoma phenotype." (PMID 38891878, 2024). "SNHG16 affects the activation of the PI3K/AKT pathway in cisplatin‐resistant neuroblastoma cells, and SNHG16 does this by regulating PLK4 expression by sponging miR‐338‐3p and the SNHG16/miR‐338‐3p/PLK4 axis effect." (PMID 35592755, 2022). "In neuroblastoma cells, SNHG16 can act as a molecular sponge for miR-338-3p to increase PLK4 expression, which in turn promotes tumor development and enhances cisplatin resistance." (PMID 36506097, 2022). "SNHG1 and PLK4 were increased in neuroblastoma tissue and cells, whereas the expression of miR‐338‐3p decreased and targets of miR‐338‐3p and SNHG1 or PLK4 were elucidated." (PMID 35592755, 2022).
neuroblastoma (continued). "Consistently, we confirm that three centrinone targets, the tyrosine phosphatase PTPN12, the neuroblastoma-driving transcription factor NMYC and PLK4 itself, are directly phosphorylated by recombinant PLK4 in vitro." (PMID 32501498, 2020). "It has been reported that PLK4 expression involved in the phosphoinositide 3-kinase/threonine-protein kinases signaling pathway, thus increased the EMT-related proteins expression of neuroblastoma cells." (PMID 35912011, 2022). "Polo-like kinase 4, a key molecule regulating centriole replication, promotes neuroblastoma tumorigenesis and metastasis through the PI3K/AKT pathway in cell lines and animal models, and the knockdown of AKT induced neuroblastoma apoptosis under hypoxia." (PMID 35454815, 2022). "In this study, we demonstrated that PLK4 expression positively correlated with primary site, serum level of lactate dehydrogenaserelapse (LDH), recurrence, expression level of Ki-67, clinical stage by International Neuroblastoma Staging System (INSS), and poor prognosis." (PMID 29352113, 2018).
hepatocellular carcinoma (18 papers, 2009 to 2025). A malignant tumor that arises from hepatocytes. "In hepatocellular carcinoma, downregulation of PLK4 is reported to be linked to larger tumor size and poor prognosis as it has been observed for overexpressed PLK4." (PMID 34065956, 2021). "Thus, we aimed to investigate whether genetic variants in PLK4 contribute to the development of hepatocellular carcinoma (HCC)." (PMID 31489978, 2019). "In mice, Plk4 is haploinsufficient for tumour suppression, while in humans, loss of heterozygosity (LOH) for the Plk4 gene was found in 60% of a small sample of human hepatocellular carcinomas (HCC) cases." (PMID 21324136, 2011). "In contrast, in hepatocellular carcinoma, PLK4 was considered as a inhibitory factor of tumorigenesis and progression." (PMID 36176741, 2022). "Lack of FAM46C/TENT5C function, now revealed as a frequent and prognostic feature in human colorectal cancer as well as in multiple myeloma and hepatocellular carcinoma, can promote tumor progression by allowing unrestrained Plk4 activity." (PMID 32807875, 2020). "Plk4 loss also has implications in human malignancy, where LOH for Plk4 was found in the majority of a small sample of hepatocellular carcinomas." (PMID 19607708, 2009). "For example, PLK4 is highly expressed in breast cancer but low in hepatocellular carcinoma." (PMID 36176741, 2022). "Besides, PLK4 was also overexpressed and promoted the progression of melanoma, hepatocellular carcinoma and brain tumors." (PMID 36051696, 2022). "PLK4 overexpression improved cell proliferation and invasion of hepatocellular carcinoma." (PMID 34080290, 2021). "CFI-400945 inhibits the proliferation of cancer cells with highly expressed PLK4; suppresses liver cancer progression through cell cycle inhibition and induces antitumor immunity; centrinone B treatment decreases the viability of different hepatocellular carcinoma cell lines." (PMID 41092110, 2025). "Thus, our data show that YAP inactivation serves as a downstream event of lncRNA PLK4 down‐regulation, and triggers tumour cell senescence, which might be the key mechanism that talazoparib inhibits hepatoma cell growth." (PMID 32243714, 2020). "Polo-like kinase 4 (PLK4), originally identified in Drosophila as a serine/threonine kinase and mapped to chromosome 4 q28 which is a region frequently associated with loss of heterozygosity (LOH) in hepatoma, is essential for centriole duplication and cell cycle progression." (PMID 22829937, 2012). "Mechanistically, talazoparib inhibits tumour cell growth through promoting lncRNA PLK4 up‐regulation specifically, followed by YAP inactivation, ultimately leading to cellular senescence of hepatoma cells." (PMID 32243714, 2020). "PLK4 has been proposed as a tumor suppressor in hepatocellular carcinoma (HCC)." (PMID 22829937, 2012). "Genome-wide screen by CRISPRa library in vivo for drivers of hepatocellular carcinoma (HCC) progression revealed that overexpression of XAGE1B, PLK4, LMO1 and MYADML2 genes promoted HCC cell proliferation and invasion, which were suppressed by their inhibition." (PMID 39696697, 2024). "In this study, we identified a novel function lncRNA, named polo‐like kinase 4 associated lncRNA (lncRNA PLK4, GenBank Accession No. RP11‐50D9.3), whose expression was dramatically down‐regulated in hepatocellular carcinoma (HCC) tissues and cells." (PMID 32243714, 2020).